IGF2BP1 (insulin like growth factor 2 mRNA binding protein 1)
Diseases named in the same sentence as IGF2BP1 in open-access papers (continued):
Sharing a sentence is not in itself a finding about the gene and the disease.
hepatocellular carcinoma (continued). "In human hepatocellular carcinoma (HCC) and hepatoblastoma cells, IGF2BP1 binds to the 3′UTR of SLC7A11 mRNA, enhancing its stability and preventing deadenylation." (PMID 40271153, 2025). "LINC00665 can modulate 11 mRNAs by regulating m6A enzymes YTHDF1, IGF2BP1, and IGF2BP2 in hepatocellular carcinoma (HCC)." (PMID 38351139, 2024). "In addition, F-box/SPRY domain-containing protein 1 (FBXO45), an E3-ubiquitin ligase, was found to promote IGF2BP1 ubiquitination and attenuate hepatocellular carcinoma (HCC) progression." (PMID 36632454, 2023). "In hepatocellular carcinoma, lnc-CTHCC, stabilized by METTL3/IGF2BP1/IGF2BP3 via m6A modification, promotes tumor initiation and development by binding hnRNPK and activating YAP1 transcription." (PMID 37280679, 2023). "In hepatocellular carcinoma (HCC), miR-98-5p could restrain cell proliferation and induce cell apoptosis via inhibition of its target gene IGF2BP1." (PMID 35578599, 2022). "miR-9-5p enhances the tumorigenic ability of hepatocellular carcinoma cells by targeting CPEB3 and ESR1, but miR-9 plays a tumor suppressor role in hepatocellular carcinoma by regulating IGF2BP1, Sox11, and P21." (PMID 36421826, 2022). "For example, the RBP IGF2BP1 binds to and destabilizes the lncRNA HULC in human hepatocellular carcinoma." (PMID 34803608, 2021). "IGF2BP1 overexpression promotes hepatocellular carcinoma (HCC) progression." (PMID 32917856, 2020). "miR-9 is frequently down-regulated in primary hepatocellular carcinoma and its restoration retards cell proliferation and migration by targeting IL-6, AP3B1, TC10, OC2, IGF2BP1, MYO1D, and ANXA241." (PMID 32393810, 2020). "A recent study has reported that a new lncRNA HCG11-derived oncogenic growth through interaction with the RNA-binding protein IGF2BP1, contributes in facilitating the ERK/MAPK pathway in hepatocellular carcinoma." (PMID 29416735, 2018). "For example, IGF2BP1 is involved in liver carcinogenesis by binding to and stabilizing the c-MYC and MKI67 mRNAs, and it is an important pro-tumorigenic factor for hepatocellular carcinoma." (PMID 27588393, 2016). "IGF2BP1 can recognize circMDK via m6A sites, activate the PI3K/AKT/mTOR signaling pathway through the miR-346/874-3p-ATG16L1 axis, and ultimately promote the proliferation, migration and invasion of hepatoma cells." (PMID 39229278, 2024). "In addition, IGF2BP1 reduces the stability of HULC mRNA, which is specifically and highly expressed in hepatocellular carcinoma." (PMID 37631029, 2023). "Moreover, IGF2BP1 elevates the expression of Polo like kinase 1 (PLK1), thus inhibiting the apoptosis of hepatocellular carcinoma (HCC) cells." (PMID 37554271, 2023). "IGF2BP1 interacts with and stabilizes GLI1 mRNA from decay in hepatocellular carcinoma." (PMID 37149646, 2023). "Moreover, LINC01138 has been reported as a tumor promoter that can exert its biological functions via the tumor-related IGF2BP1/IGF2BP3-LINC01138-PRMT5 axis in hepatocellular carcinoma (HCC), which can serve as a robust biomarker and therapeutic target for HCC." (PMID 35506372, 2022). "In hepatocellular carcinoma (HCC), the cancer-testis lncRNA-CTHCC promotes HCC growth and metastasis, and mechanistically, lncRNA-CTHCC is modified by m6A methylation with METTL3 and IGF2BP1/IGF2BP3 to maintain its stability and increase its expression." (PMID 35541906, 2022). "Notably, a previous report showed that ALKBH5-mediated m6A modification of LY6/PLAUR Domain Containing 1 (LYPD1) is recognized by IGF2BP1 and enhances the stability of LYPD1 mRNA in hepatocellular carcinoma." (PMID 35318440, 2022). "Additionally, IGF2BP1 has shown to activate ERK, JNK, and p38 MAPKs, which eventually promoted the progression of hepatocellular carcinoma cells, therefore, we cannot exclude the possibility there is a reciprocal regulatory loop between ERK1/2 and IGF2BP1." (PMID 33747724, 2021).
hepatocellular carcinoma (continued). "More recent work suggests that IGF2BP1, YTHDF1 and YTHDF1 mainly function as oncogenes in multiple cancer types, including colorectal cancer, hepatocellular carcinoma (HCC), gastric cancer, lung cancer, AML, pancreatic cancer, OC, bladder cancer, prostate cancer and melanoma." (PMID 34895230, 2021). "Similarly, studies have also reported the tumor-promoting role of IGF2BP1, IGF2BP3, IGFBP6 and IGFL2 in several cancers such as hepatocellular carcinoma, pancreatic and prostate cancers." (PMID 34061869, 2021). "Consistently, IGF2BP1 expression is associated with poor prognosis in various human cancers and the protein enhances the growth and metastasis of human tumor-derived cells in nude mice, as demonstrated for epithelial ovarian cancer (EOC) as well as hepatocellular carcinoma (HCC) derived tumor cells." (PMID 30371874, 2019). "On the one hand, IGF2BP1 protects the degradation of PTEN mRNA and thus promotes the migration of tumor cells, while on the other hand, IGF2BP1 promotes the expression of C-Myc and MKI67 mRNA to regulate the proliferation and apoptosis of hepatocellular carcinoma cells." (PMID 37631029, 2023).
ovarian carcinoma (53 papers, 2010 to 2025). A malignant neoplasm originating from the surface ovarian epithelium. "IGF2 mRNA binding protein 1 (IGF2BP1) belongs to the IGF binding protein family, and an ovarian cancer risk score model showed that IGF2BP1 shared great value in the prognostic analysis of ovarian cancer cases." (PMID 37304234, 2023). "Elevated IGF2BP1 expression was also associated with ovarian carcinoma and proliferation deregulation through a c-myc (MYC) dependent mechanism." (PMID 24086150, 2013). "Expression of IGF II mRNA-binding protein produced by IGF2BP1 has been implicated in ovarian cancer." (PMID 23704328, 2013). "It selectively decreases the expression of the mRNA targets of IGF2BP1, including MYC, by limiting the association between IGF2BP1 and the coding region stability determinants of its target mRNAs, eventually suppressing the proliferation of melanomas and ovarian cancer cells." (PMID 37554271, 2023). "The m6A regulators RBM15, ZC3H13, YTHDF1, and IGF2BP1 may cause ovarian cancer immune infiltration." (PMID 37194218, 2023). "In lung adenocarcinoma and ovarian cancer, m6A/IGF2BP1-mediated mRNA stabilizations of endothelin-converting enzyme 2 (ECE2) and circRNA nuclear factor I (circNFIX) are also crucial for tumor cells to enhance immunosuppression." (PMID 40584294, 2025). "Long non-coding RNA (LncRNA) MCF2L-AS1 contributes to cisplatin resistance of ovarian cancer via regulating the IGF2BP1/IGF2/MEK pathway." (PMID 39759028, 2024). "In colocalization analysis, we noticed that CACNA1G-AS1, FTH1 (green) and IGF2BP1 (red) colocalized in the cytoplasm of ovarian cancer cells." (PMID 37304234, 2023). "All these results revealed that the FTH1 m6A methylation regulation pathway (CACNA1G-AS1/IGF2BP1) is closely related to ovarian cancer progression." (PMID 37304234, 2023). "All these results showed that the amount of CACNA1G-AS1 and FTH1 pulled down by the AGO2 antibody significantly increased in ovarian cancer cells transfected with IGF2BP1." (PMID 37304234, 2023). "The results revealed that the colocalization of autophagy regulator (LC3) and lysosome (LAMP2) significantly increased in CACNA1G-AS1 knockdown ovarian cancer cells, while IGF2BP1 upregulation reversed this change." (PMID 37304234, 2023). "Through pathway expression verification, we confirmed that the FTH1 m6A methylation regulatory pathway (CACNA1G-AS1/IGF2BP1) was obviously increased in ovarian cancer samples, and its expression was closely related to tumor malignancy." (PMID 37304234, 2023). "In this section, we overexpressed IGF2BP1 in ovarian cancer cells and coimmunoprecipitated target RNA with an anti-AGO2 antibody." (PMID 37304234, 2023). "The abnormal expression of m6A-related regulatory enzymes including METTL3, FTO, ALKBH5, IGF2BP1, YTHDF1, and YTHDF2 is closely linked with the growth, metastasis, invasion, and chemotherapy resistance in ovarian cancer." (PMID 37781028, 2023). "Previous study has revealed that IGF2BPs contribute to mRNA stability and IGF2BP1 and IGF2BP3 are associated with poor disease outcome in ovarian cancer." (PMID 35869392, 2022). "For instance, BTYNB, a selective inhibitor of IGF2BP1, reduces IGF2BP1 protein expression and retards ovarian cancer growth by impairing interactions between IGF2BP1 and c-MYC or E2F1 mRNA." (PMID 35794625, 2022). "There is evidence that IGF2BP1 expression is increased in ovarian cancer cells cultured in vitro, while MYC expression is maintained." (PMID 34794452, 2021). "IGF2BP1 was a miR-708 target, and overexpression of IGF2BP1 restored cisplatin resistance by promoting Akt phosphorylation in miR-708-overexpressing ovarian cancer cells." (PMID 34203267, 2021). "In conclusion, m6A RNA methylation regulators are vital participants in ovarian cancer pathology; and IGF2BP1, VIRMA, and ZC3H13 mRNA levels are valuable factors for prognosis prediction and treatment strategy development." (PMID 32950970, 2020).
ovarian carcinoma (continued). "In ovarian cancer, IGF2BP1 enhances cell proliferative and invasive ability by antagonizing miRNA-impaired gene expression, the elevate expression of IGF2BP1 is correlated to poor prognosis." (PMID 33015074, 2020). "IGF2BP1 was reported to be significantly elevated in cervical cancer (CC) tissues and cell lines and in ovarian cancer tissues." (PMID 29954406, 2018). "In ovarian carcinoma (OC) cells, IGF2BP1 was showed to act as an oncogenic factor that contributes to enhanced proliferation by stabilizing the c-MYC mRNA." (PMID 29954406, 2018). "Tumors had frequent and multiple deletions of miRs with predicted targets for IGF2BP1, an mRNA-binding protein with a suspected tumorigenic role in several malignancies, including pancreatic, colorectal, breast, and ovarian cancers." (PMID 28486549, 2017). "In agreement, we reported that IGF2BP1 promotes the directed migration of tumor cells derived from osteosarcoma, ovarian carcinoma as well as glioblastoma." (PMID 23677615, 2013). "Among them, IGF2BP1 emerged as a dominant immune evasion driver in C5-like ovarian cancer." (PMID 41444249, 2025). "IGF2BP1 could attenuate the tumor suppressive effect of cisplatin and induce cisplatin resistance in ovarian cancer, oral squamous cell carcinoma, seminoma, and endometrial cancer cells by regulating its target mRNA stabilization." (PMID 40584294, 2025). "The immune-evasive yet druggable nature of IGF2BP1 in ovarian cancer cells suggests that inhibiting IGF2BP1-RNA interactions with small-molecule inhibitors such as BT or CUB may enhance T cell-mediated tumor cell killing." (PMID 41444249, 2025). "In ovarian cancer, expression of IGF2BP1 is negatively correlated with immune cell infiltration." (PMID 39028290, 2024). "Scratch tests showed that the proportion of transversally migrated cells in CACNA1G-AS1-overexpressing ovarian cancer cells obviously increased (p < 0.01), while the proportion of migrated cells correspondingly decreased after IGF2BP1 and FTH1 inhibition (p < 0.01)." (PMID 37304234, 2023). "ROS and Fe2+ detection showed that in CACNA1G-AS1-overexpressing ovarian cancer cells, the ROS and Fe2+ contents significantly decreased, while these changes could be reversed by IGF2BP1 and FTH1 inhibition." (PMID 37304234, 2023). "In vitro cell experiments showed that LncRNA CACNA1G-AS1 could up-regulate FTH1 expression through IGF2BP1 axis, thus inhibited ferroptosis by regulating ferritinophagy, and finally promoted proliferation and migration in ovarian cancer cells." (PMID 37304234, 2023). "According to these results, we concluded that CACNA1G-AS1 could inhibit ferritinophagy via IGF2BP1-mediated FTH1 methylation in ovarian cancer cells." (PMID 37304234, 2023). "According to these results, we concluded that CACNA1G-AS1 could upregulate FTH1 via IGF2BP1-mediated m6A methylation in ovarian cancer cells." (PMID 37304234, 2023). "First, we detected the colocalization of ferritin and lysosome labels, and the results confirmed that the colocalization of ferritin (FTH1) and lysosome (LAMP2) significantly increased in CACNA1G-AS1 knockdown ovarian cancer cells, while IGF2BP1 upregulation reversed this change." (PMID 37304234, 2023). "Cell function experiments confirmed that CACNA1G-AS1 could inhibit mitophagy and promote malignant phenotypes in ovarian cancer cells through IGF2BP1-mediated FTH1 m6A methylation." (PMID 37304234, 2023). "In contrast, in CACNA1G-AS1 knockdown ovarian cancer cells, the ROS and Fe2+ contents significantly increased, while these changes could be reversed by IGF2BP1 and FTH1 upregulation." (PMID 37304234, 2023). "In CACNA1G-AS1 knockdown ovarian cancer cells, the ROS contents significantly increased, and these changes could be reversed by IGF2BP1 and FTH1 overexpression." (PMID 37304234, 2023).
ovarian carcinoma (continued). "The expression of IGF2BP1 and FTH1 was strongly linked to ovarian cancer grade malignancy." (PMID 37304234, 2023). "The results confirmed that in CACNA1G-AS1-overexpressing ovarian cancer cells, the red fluorescence intensity obviously increased, while these changes could be reversed through IGF2BP1 and FTH1 inhibition." (PMID 37304234, 2023). "IGF2BP1 is an invasive growth driver of ovarian cancer targeting the SRC/MAPK signaling pathway." (PMID 36110943, 2022). "Several target genes of miR-140-5p have been identified, including platelet-derived growth factor receptor A (PDGFRA) in ovarian cancer, insulin-like growth factor 2 mRNA-binding protein 1 (IGF2BP1) in cervical cancer, and YES proto-oncogene 1 (YES1) in gastric cancer." (PMID 30962263, 2019). "IGF2BP1 regulates the growth factor IGF2, and knockouts of the gene in mice suggest a role in organ development, while its expression is associated with ovarian cancer." (PMID 20195514, 2010). "Moreover, in CACNA1G-AS1 knockdown ovarian cancer cells, red fluorescence intensity was obviously reduced, while these changes could be rescued through IGF2BP1 and FTH1 overexpression." (PMID 37304234, 2023). "According to risk score models, patients with ovarian cancer who had low VIRMA or high HNRNPA2B1 expression had prolonged half survival, and the constructed miRNA-m6A regulator (VIRMA, IGF2BP1, HNRNPA2B1)-target gene regulatory network could predict the prognosis of OC patients." (PMID 37194218, 2023). "Furthermore, IGF2BP1 can promote ferroptosis resistance by stabilizing ferritin heavy chain 1 (FTH1), signal transducer and activator of transcription 3 (STAT3), and parkinsonism-associated deglycase (PARK7) mRNAs in HCC, bladder cancer, ovarian cancer, and GC, respectively." (PMID 40584294, 2025). "The results showed that in CACNA1G-AS1 knockdown ovarian cancer cells, FTH1 and IGF2BP1 expression significantly decreased, while IGF2BP1 overexpression reversed this change." (PMID 37304234, 2023). "In contrast, in CACNA1G-AS1-overexpressing ovarian cancer cells, FTH1 and IGF2BP1 expression obviously increased, while IGF2BP1 downregulation reversed this change (consistent with IGF2BP1)." (PMID 37304234, 2023). "SKOV3 cells were transfected with plasmids containing RNA mimics and inhibitors (CACNA1G-AS1, IGF2BP1 and FTH1) to construct ovarian cancer cell models with different pathway expression states." (PMID 37304234, 2023). "The results confirmed that compared with ovarian cells and tissues, CACNA1G-AS1, IGF2BP1 and FTH1 expression levels were obviously increased in ovarian cancer samples." (PMID 37304234, 2023). "The observation of mitochondrial morphology revealed that in CACNA1G-AS1 knockdown ovarian cancer cells, the mitochondrial volume was obviously reduced, the mitochondrial membrane was ruptured and the cristae vanished, while these changes could be rescued by IGF2BP1 and FTH1 overexpression." (PMID 37304234, 2023). "We constructed ovarian cancer cell models with different expression levels of CACNA1G-AS1 and IGF2BP1 and then performed WB to detect FTH1 and IGF2BP1 expression." (PMID 37304234, 2023). "Colony formation assays confirmed that the number of newly generated cells in the CACNA1G-AS1 overexpression group obviously increased, while this number correspondingly decreased after IGF2BP1 and FTH1 inhibition in ovarian cancer cells (p < 0.01)." (PMID 37304234, 2023). "EdU assays showed that the proportion of new cells in the CACNA1G-AS1 overexpression group obviously increased (p < 0.01), while this proportion correspondingly decreased after IGF2BP1 and FTH1 inhibition in ovarian cancer cells (p < 0.01)." (PMID 37304234, 2023). "Several other Igf2bp1 target RNAs (SRF, cMyc, and CD44) are reduced in lung and ovarian carcinoma cells incubated with the compound." (PMID 34895045, 2022).